IL22 (interleukin 22)
Diseases named in the same sentence as IL22 in open-access papers (continued):
Sharing a sentence is not in itself a finding about the gene and the disease.
psoriasis (continued). "Bioptic samples from PV plaques show elevated levels of IL-17 in parallel with increased expression of IL-23 and IL-22, while serum levels of IL-17 are correlated to psoriasis severity." (PMID 25126586, 2014). "IL-23 promotes the maintenance of T cells producing IL-17 and IL-22, which are abundant in and contribute to many of the hallmarks seen in psoriasis." (PMID 25216727, 2014). "IL-22 plays an important role in the pathogenesis of T cell-mediated inflammatory diseases such as psoriasis, inflammatory bowel disease and rheumatoid arthritis." (PMID 25208211, 2014). "Both these observations suggest that aberrant silencing of miRNAs takes part in the pathogenesis of psoriasis by allowing the un-controlled signaling of IL-22 and IGF1R, respectively." (PMID 25208211, 2014). "In previous studies, Th22 cells and IL-22 often showed to correlate with disease severity, such as in the patients with rheumatoid arthritis and psoriasis." (PMID 24899787, 2014). "A complex cytokine network has been described in psoriasis and highlighted a central role of proinflammatory cytokines such as IL-23, IL-22, IL-17, IL-1 or TNFα produced by infiltrated immune cells." (PMID 25010647, 2014). "Currently, Phase I and Phase II clinical trials based on anti-IL-22 therapies are on going for atopic dermatitis, psoriasis, and rheumatoid arthritis." (PMID 25254361, 2014). "In psoriasis, a benign inflammatory skin disease characterized by hyperproliferative keratinocytes, IL-22 induces inflammation, mediates keratinocyte proliferation, and inhibits keratinocyte terminal differentiation." (PMID 23667456, 2013). "Some types of Th17 also produce IL-22 that has a pathogenetic role in psoriasis but a protective one in IBD." (PMID 23971052, 2013). "Skin biopsy samples from patients with psoriasis showed elevated expression levels of IL-17 together with high expression of IL-23 and IL-22." (PMID 23956763, 2013). "The treatment with IL-22-neutralizing antibodies in a psoriasis-like mouse model prevents the development of symptoms, in particular acanthosis is ameliorated and inflammatory infiltrates and the expression of Th17 cytokines is reduced." (PMID 23531535, 2013). "In contrast, in the IL-23-induced psoriasis model, IL-22 is required for the development of dermal inflammation and acanthosis." (PMID 23472158, 2013). "It is on that basis, we discovered that curcumin can suppress inflammation in IMQ-induced psoriasis-like mice model and decrease the cytokines production, such as IL-17A, IL-17F, IL-22, IL-1β and TNF-α." (PMID 23825622, 2013). "The aim of this study was to characterize interleukin 17 (IL-17) and interleukin 22 (IL-22) producing cells in peripheral blood (PB), skin, synovial fluid (SF) and synovial tissue (ST) in patients with psoriasis (Ps) and psoriatic arthritis (PsA)." (PMID 24286492, 2013). "In psoriasis, IL-23 is produced at high levels by DCs and keratinocytes, and this cytokine stimulates Th17 cells to produce IL-17A and IL-22." (PMID 23956763, 2013). "In contrast to the application of IL-22, IL-22 transgenic mice exhibit a different psoriasis-like phenotype." (PMID 23531535, 2013). "Overall, targeting IL-22 or its receptors represents a promising approach to ameliorate the outcome of autoimmune diseases such as psoriasis or psoriatic." (PMID 23460846, 2013). "IL-22, another important cytokine for psoriasis pathogenesis, can be produced by CD4+ T and CD8+ T cells." (PMID 23468834, 2013). "The expression of IL-22 in IMQ-induced psoriasis-like inflammation was also markedly down-regulated by curcumin." (PMID 23825622, 2013). "For instance, IL-22 plays a protective role in Con A-induced acute hepatitis but a pro-inflammatory role in psoriasis." (PMID 23956763, 2013). "In our previous study, photo(chemo)therapy significantly reduced the increased serum levels of both IL-17 and IL-22 in psoriasis patients compared to those in healthy volunteers." (PMID 23365685, 2013).
psoriasis (continued). "Altogether, present data suggest IL-22 as promising target for immunomodulation in psoriasis patients." (PMID 23382730, 2013). "Another study also showed that IL-22 is required for psoriasis-like lesions in the mouse Imiquimod model." (PMID 23956763, 2013). "IL-22 induces anti-microbial proteins such as beta-defensins and IL-22 mRNA expression is increased in psoriasis lesions compared to normal skin." (PMID 23468834, 2013). "Th17 cells producing IL-17, IL-22, and tumor necrosis factor-α are pathogenically related to psoriasis." (PMID 23365685, 2013). "Recently, Th17 cells have been suggested to be involved in the pathogenesis of psoriasis synthesizing IL-17A, IL-17F, and IL-22." (PMID 23213332, 2012). "The discovery of a role for IL-17-producing T helper cells (Th17) in psoriasis and for IL-22 producing (Th22) cells in AD emphasize the complexity of cytokine network involved in the induction and/or maintenance of these disorders." (PMID 23193414, 2012). "Because IL-17, IL-22 and IL-21 have been largely implied in skin homeostasis as well as inflammatory skin disorders such as psoriasis and atopic dermatitis, it is of importance to know which skin DC can induce the cytokine-producing T cells." (PMID 23226194, 2012). "In our hands, IL-22 expression in lesional AD and psoriasis was enhanced when compared to normal skin (submitted results)." (PMID 23193414, 2012). "Higher expression of IL-22 mRNA was observed in psoriatic skin lesion, and elevated serum IL-22 levels were found in patients with psoriasis." (PMID 22485125, 2012). "In these models, we finally analyzed the effects of the change from IL-17 (Th17, psoriasis) to IL-4/IL-13 (Th2, AD), in the same cytokine background (TNFα and IL-22)." (PMID 23193414, 2012). "IL-22 has complex functions and has been shown to produce both inflammatory (psoriasis, rheumatoid arthritis) and protective (irritable bowel disease) responses." (PMID 22888330, 2012). "Consistent with psoriasis, increased IL-22 has also been found in serum samples from RA and Crohn disease patients." (PMID 22485125, 2012). "As their effector molecule, IL-22 positively correlates with the severity of psoriasis and is highly expressed in the serum and skin lesions of psoriasis patients." (PMID 22808266, 2012). "In the pathogenesis of various autoimmune diseases such as psoriasis and RA, the role of IL-22 has been established." (PMID 22417743, 2012). "In psoriasis, a correlation between serum IL-22 level and psoriasis area and severity index (PASI) score has been observed." (PMID 22417743, 2012). "Elevated IL-22 expression is found in the serum and skin lesions of psoriasis patients and is correlated with the severity of the disease." (PMID 22808266, 2012). "For instance, the frequency of IL-22+ T cells in skin derived T-cell lines from psoriasis, atopic eczema and allergic contact dermatitis was significantly higher than in the peripheral blood." (PMID 21996293, 2011). "Th17 cells are highly involved in the development and maintenance of psoriasis, and a possible role for IL-17, IL-22, and Th17 cells in atopic dermatitis or allergic contact dermatitis is emerging." (PMID 21612588, 2011). "These T cells produce large amounts of IFN-γ, IL-17 and IL-22, leading to the skin changes observed in human psoriasis." (PMID 21311769, 2011). "In human studies, IL-22 has been proposed to play a role in the pathogenesis of autoimmune inflammatory diseases, such as psoriasis and Crohn's disease." (PMID 20929536, 2010). "Although recent studies indicate a crucial role for IL-17A and IL-22 producing T cells in the pathogenesis of psoriasis, limited information is available on their frequency and heterogeneity and their distribution in skin in situ." (PMID 21124836, 2010). "Because of its property to promote acanthosis, IL-22 is highly relevant for the pathogenesis psoriasis." (PMID 21124836, 2010).
psoriasis (continued). "Th17 cell type is specialized in the immunosurveillance of the epithelium, and also secretes high levels of IL-22, a key cytokine linking adaptive immune effectors and epithelial dysregulation in psoriasis." (PMID 20847812, 2010). "Together, these findings argue for a particular role of IL-22 mediating epidermal acanthosis and tissue inflammation in psoriasis after induction by IL-23." (PMID 19884985, 2009). "It has been demonstrated that IL-22, a well-known Th17 cytokine, mediates IL-23-induced acanthosis in a mouse model of psoriasis." (PMID 19884985, 2009). "The initial evidence linking IL-22 to psoriasis pathogenesis emerged from genetic studies." (PMID 40731810, 2025). "Furthermore, oral curcumin has shown to be quite successful in lowering serum IL-22 levels in psoriasis patients." (PMID 40690118, 2025). "Interestingly, despite elevated IL-22 levels in both diseases, it seems that blocking IL-22 lacks efficacy in psoriasis and has modest results in AD treatment." (PMID 39859462, 2025). "The actions of IL-22 are mediated through the transmembrane receptor complex comprising IL-22R1 and IL-10R2, with IL-22R1 likely playing a significant role in the pathogenesis or exacerbation of psoriasis." (PMID 40303401, 2025). "Here, we demonstrated that FTY720 treatment ameliorated the manifestations of psoriasis (erythema, scaling, and infiltration) and reduced the synthesis of inflammatory cytokines (Il22, Il23, and Tnf), showing anti-inflammatory effects and anti-proliferative effects." (PMID 39833165, 2025). "Pro-inflammatory cytokines like TNF-α, IL-17A/F, and IL-22 play a major role in psoriasis." (PMID 40507817, 2025). "Neutralizing Abs against IL-22 are being investigated for the treatment of psoriasis." (PMID 39630234, 2025). "People with psoriasis often have elevated IL-22 levels in their blood." (PMID 40690118, 2025). "Notably, IL-22 induces IL-20 production in KCs, which is also a key mediator of the epidermal alteration in psoriasis, and exerts very similar effects on KCs as IL-22 does, partially mediating certain effects of IL-22 on KCs." (PMID 41467015, 2025). "Additionally, γδ T cells contribute to psoriasis by secreting pro-inflammatory cytokines such as IL-17A, IL-17F, and IL-22, promoting inflammation and keratinocytes proliferation." (PMID 40406126, 2025). "CTLs secrete IL-2, IFN-γ, TNF-α, IL-17, and IL-22, which contribute to psoriasis development." (PMID 40906403, 2025). "However, in individuals with psoriasis, IL-22 is believed to promote keratinocyte proliferation, leading to enhanced keratinization and the development of psoriatic lesions." (PMID 40303401, 2025). "In mice with overexpressed IL-36α in keratinocytes but an otherwise normal phenotype, 12-O-tetradecanoylphorbol-13-acetate (TPA) treatment results in a considerable increase in skin inflammation that morphologically mimics psoriasis, as well as a significant rise in IL-17A, IL-22, and IL-23." (PMID 40563994, 2025). "While atopic dermatitis is characterized by a predominantly Th2 immune response, psoriasis involves more complex activation of Th1, Th17 pathways, and cytokines such as IL-17, IL-22, and IL-23, which may require more specific and targeted microbial strategies." (PMID 41304102, 2025). "Additionally, abnormal toll-like receptor expression and dendritic cell activation in both the gut and skin further exacerbate inflammation in IBD and psoriasis, with cytokines like IL-17, IL-22, and IL-12 playing distinct roles in these diseases." (PMID 39463646, 2024). "Similarly, for patients with psoriasis, a correlation between increasing IL-22 levels and increased disease severity was shown." (PMID 38612795, 2024). "Conversely, the upregulation of hBDs in psoriasis may be related to higher levels of IL-17, IL-22, and IFN-γ in the skin lesions of psoriasis patients." (PMID 38606161, 2024). "In psoriasis, the mast cells express and release IL-17 and IL-22." (PMID 39239353, 2024).
psoriasis (continued). "Psoriasis-like erythematous appearance and microscopic features were significantly reduced, along with a notable decrease in the tissue gene expression of core psoriasis cytokines, such as IL-23, IL-17A, IL-22, TNF-α, and IL-6, after the capsaicin treatment." (PMID 39338338, 2024). "Therefore, we plan to verify in a future study the role of POE in an in vitro model of psoriasis using both the hyperproliferative model of LPS/IL-22-stimulated HaCaT cells and the inflammatory model of HaCaT cells stimulated with LPS/TNF-α." (PMID 39057409, 2024). "Upon binding, IL-22 activates downstream signals in keratinocytes, inducing antimicrobial protein production and inhibiting keratinocyte differentiation, contributing to psoriasis-like epidermal inflammation." (PMID 38892253, 2024). "Furthermore, we examined a set of inflammatory cytokines, including IL-17A, IL-23A, IL-1β, TNF-α, IL-6, and IL-22, at the mRNA level in LPS-induced psoriatic keratinocytes, which are closely related to psoriasis in vivo." (PMID 39109246, 2024). "The involvement of IL-22 is significant in the pathogenesis of pediatric psoriasis, suggesting that it could serve as a unique therapeutic target specifically for this population." (PMID 39195286, 2024). "Thus, the IL-23/IL-17/IL-22 axis serves as a critical component of a positive feedback loop that promotes psoriasis progression, involving key players such as keratinocytes, DCs, and γδΤ lymphocytes." (PMID 38902277, 2024). "NK cells may contribute to the development of fibrosis by releasing IFN- γ, TNF, and IL-22, among other cytokines, in psoriasis and MASLD." (PMID 38917217, 2024). "However, new T-cell populations, such as IL-22 and Th22 cells, have recently been highlighted due to their potential role in psoriasis and IBD." (PMID 38879568, 2024). "Furthermore, TNF-α, interferon-γ (IFN-γ), IL-6, and IL-22 have also been reported to be increased in psoriasis." (PMID 39109246, 2024). "Psoriasis is characterized by keratinocyte hyperproliferation, a process driven by IL-17 and IL-22." (PMID 38926337, 2024). "IL-22 levels in serum have been shown to correlate with PASI of psoriasis patients, and psoriasis patients colonized with toxigenic strains of Staphylococcus aureus had significantly higher levels of IL-22 in serum compared with those colonized with non-toxigenic strains." (PMID 38898675, 2024). "Additionally, a non-canonical pathway characterized by phosphotyrosine-independent massive STAT3 activation contributes to IL-22 functions and is implicated in imiquimod (IMQ)-induced psoriasis in mice." (PMID 38892253, 2024). "Moreover, research indicates that IL-17A- and IL-22-producing resident memory T cells (TRM) are enriched in the affected tissues of psoriasis patients, suggesting that these cells contribute significantly to the recurrence of the disease." (PMID 39684717, 2024). "Interestingly, notable disparities in the expression of IL-17 and IL-22 were identified when comparing pediatric psoriasis patients to both pediatric healthy controls and adult psoriasis patients." (PMID 39195286, 2024). "Furthermore, research has indicated that cells producing IL-22 and the dysregulation of IL-22 levels play a significant role in the development of psoriasis." (PMID 39195286, 2024). "IL-17A, IL-17F, and IL-22 are elevated in the sera and/or skin lesions of patients with psoriasis." (PMID 39114670, 2024). "The symptoms of psoriasis, such as thickness, erythema, and scaling, and the inflammatory cytokines levels of T-helper (Th)-17-specific cells, such as IL-17 and IL-22, and Th-1-specific cells, such as TNF-α and IL-1β, are reduced by treatment with L-EO in an IMQ-induced psoriasis mouse model." (PMID 38791435, 2024).
psoriasis (continued). "Baseline substudy serum samples from patients with psoriasis (n = 118) contained significantly (all P < .01) higher concentrations of IL-17A, IL-17F, IL-22, IL-8, CCL22/macrophage-derived chemokine (MDC), and CCL4/MIP-1β than an independent, healthy control serum cohort (n = 25)." (PMID 39114670, 2024). "In psoriasis, mast cells express and release IL-17 and IL-22." (PMID 38642273, 2024). "Additionally, studies have revealed the pivotal role of IL-22 in psoriasis pathogenesis, as it activates genes dependent on STAT3 involved in differentiation and proliferation processes." (PMID 38929716, 2024). "In addition to this, in the emerging field of the innate immune system, innate lymphoid cells (ILC) 3 in ILC appear to be important in psoriasis because of their ability to produce IL-22 and IL-17A." (PMID 39720727, 2024). "Immune-related cells including dendritic cells (DCs) and T helper (Th) 17 cells, along with Toll-like receptors(TLRs) and cytokines such as interferon (IFN)-α, tumor necrosis factor (TNF)-α, IFN-γ, Interleukin(IL)-12, IL-22, IL-23, and IL-17, are responsible for the pathogenesis of psoriasis." (PMID 38347543, 2024). "As expected, in M5‐challenged HaCaT cells, the elevated activities of inflammatory molecules that emerged as critical components in the pathogenesis of psoriasis including IL‐23, IL‐17, and IL‐22 were all prominently lowered by Wogonin, exhibiting a concentration‐dependent manner." (PMID 38967379, 2024). "Conversely, BT patients showed a distinct cytokine profile characterized by significantly reduced levels of IFN-γ, IL-2, IL-17F, and IL-22 compared to UT patients, highlighting the potent immune-modulating effects of biological treatments in attenuating pro-inflammatory pathways in psoriasis." (PMID 39769151, 2024). "Consequently, increased IL-22 expression levels have been observed in the skin and peripheral blood of patients with psoriasis compared to healthy individuals." (PMID 39195286, 2024). "IL-6 and IL-22 work synergistically with IL-17A as potent STAT3 activators in psoriasis." (PMID 38892253, 2024). "Last but not least, TBTDC NP-PDT attenuated IMQ-induced up-regulation of inflammatory cytokines, including TGF-β1, IL-1β, IL-17, IL-23, TNF-α, IFN-γ, IL-6, and IL-22, which are important proinflammatory cytokines involved in psoriasis pathogenesis in the skin lesions of mice." (PMID 39109246, 2024). "Antibodies neutralizing IL-22 have yielded promising results against psoriasis and rheumatoid arthritis, and they may improve the response to chemotherapy, especially in reducing metastases." (PMID 39201060, 2024). "Moreover, IL-23 secreted by dendritic cells and macrophages stimulate γδ T cells to secrete IL-17A, IL-17F, and IL-22 in psoriasis." (PMID 36645209, 2023). "In addition, AOA treatment significantly decreased the expression levels of Il17a, RAR related orphan receptor C (Rorc), and IL22 in ear skin of the psoriasis-like mouse model." (PMID 37649889, 2023). "The development of PN during the treatment of psoriasis with the secukinumab is clinically rare, and the etiology may be related to a Th22/IL-22 immune response imbalance, and the clear pathogenesis needs to be further investigated." (PMID 37408052, 2023). "Accordingly, recent data suggest that targeting IL-22 may prove effective in treating psoriasis and other inflammatory conditions." (PMID 38067173, 2023). "Furthermore, tapinarof exhibits direct binding to the aryl hydrocarbon receptor (AhR), leading to a reduction in the production of inflammatory cytokines, including IL-17A, IL-17F, IL-22, IL-23, and IL-1β, as demonstrated in a psoriasis-like mouse model." (PMID 38288335, 2023). "This happens for IL-6, IFN-γ, IL-22, and IL-21, all involved in psoriasis." (PMID 36901778, 2023). "In addition, different studies highlighted the vital role of IL22 in psoriasis induction, its over expression in the psoriatic lesions, and its correlation with immune cells imbalance and disease severity." (PMID 37010718, 2023).